SMAD2 (SMAD family member 2)
Diseases named in the same sentence as SMAD2 in open-access papers (continued):
Sharing a sentence is not in itself a finding about the gene and the disease.
neuroblastoma (9 papers, 2013 to 2023). Neuroblastoma (NB) is the most common solid, extracranial childhood tumor. "Galunisertib is supposed to suppress the activation of SMAD2 in neuroblastomas and activate NK cells, restore NK cytotoxic activity, and increase the efficacy of dinutuximab with activated NK cells against neuroblastoma tumors." (PMID 36534225, 2022). "It was previously demonstrated that three miRNAs of the miR-17-92 cluster target SMAD2 in neuroblastoma cells." (PMID 26545119, 2015). "For instance, Smad2 has been revealed to be a direct target of miR-18a in neuroblastoma cells." (PMID 27641158, 2016). "The role of RNF11 in the TGFβ pathway is of particular interest in neuroblastoma given our previous finding that the miR-17∼92 cluster components target TGFBR2 and SMAD2 as well as TGFβ downstream regulated genes CDKN1A, ITGA4, and SERPINE1." (PMID 23308108, 2013). "Maximal suppression of neuroblastoma tumor growth in NOD/SCID mice by NK cells in a microenvironment in which tumor cell STAT3 and SMAD2/3 pathways are active occurs when mice are treated with both lenalidomide and ch14.18." (PMID 23982484, 2013). "Former studies using activin A and a human neuroblastoma cell line demonstrated that the expression of some TGFβ superfamily target genes induced by ALK4–activin A did not require promoter bindings of SMAD2/3." (PMID 32295230, 2020).
skin cancer (9 papers, 2011 to 2021). "In contrast, loss of Smad2 in keratinocytes can accelerate skin tumor formation in the early stages and increase malignant conversion in the later stages." (PMID 25170969, 2014). "In human skin cancer, Smad2 loss was associated with dedifferentiation, and the loss of E-cadherin." (PMID 33670735, 2021). "In addition, studies in the human skin cancer patients demonstrated that the loss of the SMAD2 was linked with trans-differentiation, and with the strong reduction of E-cadherin expression." (PMID 33801157, 2021). "Compared with Smad3, Smad2 may play an antagonistic role in the EMT process in vivo: In fact, loss of Smad2 has been frequently shown in human skin cancers, and Smad2 deficiency in keratinocytes promotes EMT accelerating skin tumorigenesis." (PMID 31387321, 2019). "It has been shown that oncogenic Ras must cooperate with high TGF-β-Smad2 signaling to induce EMT in mouse skin tumour cells." (PMID 29534718, 2018). "Keratinocyte-specific Smad2 ablation resulted in increased epithelial-mesenchymal transition during skin cancer formation and progression." (PMID 27302923, 2016). "In a 2-stage chemical carcinogenesis study, Smad2+/− mice had accelerated skin tumor formation that was characterized by moderately differentiated SCC with local invasion." (PMID 23326666, 2012). "Further, mice with keratinocyte-specific Smad2 deletion displayed accelerated formation and malignant progression of chemically induced mouse skin tumors compared with wild type mice." (PMID 22539990, 2012). "Keratinocyte-specific Smad2-KO mice display accelerated skin tumor formation and progression." (PMID 25170969, 2014). "Moreover, in human skin cancer patients frequently an under expression of SMAD2 was observed." (PMID 33801157, 2021). "Moreover, underexpression of Smad2 is frequently detected in human skin cancer patients." (PMID 33670735, 2021). "The downregulation of Smad2 in SARA mutant mice contributes to increased skin tumor formation and malignant conversion, but does not affect mouse embryonic development." (PMID 25170969, 2014). "K5.Smad2-/- mice do not develop spontaneous skin tumors, but have accelerated tumor formation and malignant conversion in a two-stage chemical carcinogenesis experiment." (PMID 22204491, 2011). "Smad2 deletion in epidermal keratinocytes does not initiate tumorigenesis, but accelerates skin tumor development and malignant cancer transition." (PMID 22204491, 2011).
sarcopenia (8 papers, 2012 to 2025). Progressive decline in muscle mass due to aging which results in decreased functional capacity of muscles. "In patients with HFrEF, sarcopenia, as a strong predictor of disability and mortality, occurs as a result of numerous molecular mechanisms, including Smad2/3 signaling." (PMID 40943120, 2025). "Myopathy and sarcopenia both trigger myostatin overexpression, leading to a strong activation of the Smad2/3 path, which increases proteasomal and autophagic-lysosomal capabilities." (PMID 40943120, 2025). "Altered cholesterol homeostasis and inflammation led to a defective TGF-β1/SMAD2/3 signaling pathway, inducing fibrosis, atrophy, muscle remodeling, and sarcopenia." (PMID 36829889, 2023). "Muscle myopathy and sarcopenia are related to overexpression of myostatin that acts as powerful activator of the Smad2/3 pathway and thereby stimulates the proteasomal and the autophagic-lysosomal capabilities." (PMID 33520013, 2021). "However, being a strong predictor of frailty, disability, and mortality sarcopenia occurs in patients with HFrEF in results of abundant molecular mechanisms including Smad2/3 signaling." (PMID 33520013, 2021).
silicosis (8 papers, 2017 to 2026). Silicosis is a respiratory disease caused by breathing in (inhaling) silica dust. "Increased phosphorylation of SMAD2/3 was observed in both lungs of silicosis rats and TC-1 cells cultured with the supernatant of SiO2-stimulated RAW264.7 cells or TGF-β1 alone, which was inhibited by BIC." (PMID 39060930, 2024). "We also found that TGF-β-Smad2/3 signaling is a key regulatory target promoting macrophage transition during silicosis." (PMID 37185726, 2023). "Notably, we observed that the number of p-SMAD2/3-positive cells was significantly elevated in both silicosis patients and silicotic mice lung tissues." (PMID 37705751, 2023). "The over-expression of TGF-β, TGFβRI, TGFβRII, and p-Smad 2/3 in the lungs of silicosis mice and macrophages induced by SiO2 confirmed the activation of the TGF-β-Smad2/3 signaling pathway." (PMID 37185726, 2023). "The present study demonstrated that quercetin is a potential therapeutic agent for silicosis, which acts by regulating macrophage polarity and the MMT through the TGF-β-Smad2/3 signaling pathway." (PMID 37185726, 2023). "Since PFD reduced the severity of silicosis by inhibiting the epithelial mesenchymal transition (EMT), regulating the TGF-β 1/Smad2/3 signaling pathway, and inhibiting the production of IL-17A, we used it as a positive control in our study." (PMID 35401236, 2022). "SMAD2, a downstream molecule of the TGF-β signaling pathway, was significantly higher in PBMCs from patients with silicosis." (PMID 34517882, 2021). "The results indicated that the expression of SMAD2, MAPK3, THBS1, ITGB3, and BMP4 was increased, while the expression of SMAD3 and CD44 was significantly low expression in PBMCs from patients with silicosis, indicating consistent results with the RNA-Seq data." (PMID 34517882, 2021). "The effects were dependent on PKA/p-CREB signaling to disrupt p-Smad2/3 binding with CBP, and ultimately result in inhibition of myofibroblast differentiation in silicosis." (PMID 28222740, 2017). "As TGF-β-Smad2/3 signaling plays a critical role in fibrosis, we investigated whether it regulates the MMT during silicosis." (PMID 37185726, 2023). "In summary, we suggest that macrophage polarization and the MMT process may be important targets for silicosis, regulated by TGF-β-Smad2/3 signaling." (PMID 37185726, 2023). "Thus, the results of our study provides evidence that cAMP has anti-fibrotic effects in vitro and in vivo, and that these effects depend on PKA/p-CREB signaling by disturbing p-Smad2/3 binding with CBP, and inhibiting myofibroblast differentiation in a model of silicosis." (PMID 28222740, 2017). "Therefore, whether estrogen plays a protective role in the progression of fibrosis through the TGF β signal pathway remains to be determined, in the present study, the expression of TGF-β1 and p-SMAD2/3 of female mice and male silicosis mice was ultimately not different." (PMID 36430681, 2022).
triple-negative breast carcinoma (8 papers, 2015 to 2024). An invasive breast carcinoma which is negative for expression of estrogen receptor (ER), progesterone receptor (PR), and human epidermal growth factor receptor 2 (HER2). "In triple negative breast cancer, Asiaticoside inhibited the expression of TGF-β1 and phosphorylation of SMAD2/3, suppressing the development of triple negative breast cancer." (PMID 37685308, 2023). "Overall, our findings show clinical significance for high TMEPAI and low Smad2 in triple negative breast cancers and confirm the need to further understand the role and the regulation of TMEPAI." (PMID 31798766, 2019). "In summary, we identified a marked decrease in Smad2 protein levels to increase the Smad3 to Smad2 protein ratio in several human triple negative breast cancer cell lines." (PMID 31798766, 2019). "Our studies are the first to report that cells may escape TGF-β mediated growth suppression in triple negative breast cancer by altering endogenous Smad2 and Smad3 protein levels." (PMID 31798766, 2019). "However, this ratio is increased in most triple negative breast cancer cells (Smad3/Smad2 > 1.0) except for MDA-MB-453 cell line (Smad3/Smad2 = 0.1)." (PMID 31798766, 2019). "Interestingly, we revealed that SMAD signaling was not required for the TGF-β1-induced kisspeptin expression which is different from the previous findings that the stimulatory effect of TGF-β1 on kisspeptin is mediated by SMAD2 in triple-negative breast cancer cells." (PMID 35101033, 2022). "The triple negative breast cancer patients with higher TMEPAI/PMEPA1 and lower Smad2 mRNA expression showed decreased survival." (PMID 31798766, 2019). "Furthermore, RBMS3 has been reported to stabilise several members of the SMAD family such as SMAD2 in zebrafish and SMAD2, SMAD3 and SMAD4 in triple-negative breast cancer cells." (PMID 36421707, 2022). "Unlike in mice, where Smad2 deficiency is embryonic lethal and Smad3 deficient mice are viable and fertile, Smad3-deficiency in MDA-MB-231 triple negative breast cancer cells retarded their growth similar to TMEPAI knockdown and Smad2 deficient cells behaved like wildtype cells." (PMID 31798766, 2019).
Ureteral obstruction (8 papers, 2016 to 2025). Obstruction of the flow of urine through the ureter. "Renal tubular‐specific Glce deletion in mice exacerbated kidney fibrosis, while AAV‐mediated Glce overexpression in unilateral ureteral obstruction‐treated mice ameliorated kidney fibrosis via the TGF‐β/Smad2/3 signaling pathway." (PMID 40788059, 2025). "Rg1 inhibits renal interstitial fibrosis in rats with unilateral ureteral obstruction via suppressing both active tumor growth factor-β1 and phosphorylated Smad2, and improves anti-glomerular basement membrane-induced nephritis in rats." (PMID 34685389, 2021). "In a rat model of unilateral ureteral obstruction (UUO), oleanolic acid was found to decrease the expression of TGF-β1, the phosphorylation of Smad2, and the mRNA expression of collagen I, collagen III, and fibronectin." (PMID 33981353, 2021). "In other global kidney injury models (e.g., unilateral ureteral obstruction [UUO]), increased TGFβ1 production in the kidney alters the ratio of transcription factors Smad2 and Smad3, favoring activation of fibrosis programs." (PMID 32227630, 2020). "In contrast, unilateral ureteral obstruction in mice lacking Itga8 led to more pronounced tubulointerstitial cell activation i.e. to the appearance of more phospho-SMAD2/3-positive cells and more α-smooth muscle actin-positive cells in the tubulointerstitium." (PMID 26938996, 2016).
anemia (7 papers, 2020 to 2025). A reduction in the number of red blood cells, the amount of hemoglobin, and/or the volume of packed red blood cells. "Interestingly, dysregulated Smad2/3 signalling has also been implicated in these diseases, thus raising the possibility that luspatercept may be able to mitigate IE and anaemia in these diseases." (PMID 32351032, 2020). "In the case of MDS, overactivation of the SMAD2/3 signaling pathways contributes to anemia by impairing terminal erythroid differentiation and maturation." (PMID 39416466, 2024). "The downstream key mediators of TGF-β superfamily signaling, SMAD2/3 are constitutively activated in MDS CD34+ cells and this has been associated with impaired late-stage erythroid maturation and subsequent anemia." (PMID 36761941, 2023). "Luspatercept is a therapeutic agent that sequesters TGF-β superfamily ligands and consequently decreases SMAD2/3 activation thereby restoring erythroid maturation and improving anemia." (PMID 36761941, 2023). "RAP-536 was also shown to inhibit the overactivation of SMAD2/3 signaling, to improve anemia, and to decrease extramedullary erythropoiesis in a mouse model of β-thalassemia, also characterized by impaired erythroid maturation and ineffective erythropoiesis." (PMID 33467674, 2021). "Activin receptor-ligand trap molecules such as Sotatercept and Luspatercept downregulate the TGF-β pathway, thus inhibiting the Smad2/3 cascade and alleviating anemia in patients with β-thalassemia and myelodysplastic syndromes." (PMID 34766559, 2021). "Our study indicates that GDF11-mediated SMAD2 activation results in an increase in functionally impaired GATA1 isoforms, consequently contributing to anemia and influencing responses to luspatercept in MDS." (PMID 40424086, 2025).
endometriosis (7 papers, 2018 to 2024). The growth of functional endometrial tissue in anatomic sites outside the uterine body. "Next, we examined the association of Nodal expression with the TGF-β/Smad2 signal pathway in endometriosis and OCCCa/OEmCa." (PMID 30943930, 2019). "The presence of miR-141, EMT, and TGF-β1/SMAD2 signalling markers were detected in eutopic and ectopic endometria of endometriosis." (PMID 31903498, 2020). "In this study, we aimed to elucidate the role of TGF-β1/SMAD2 signalling in the miR-141-mediated effects of growth and metastasis of endometriosis." (PMID 31903498, 2020). "Notably, TRIM59 in ectopic lesions, through ubiquitination, regulates PPM1A degradation, activating the TGF-β/SMAD2/3 pathway and thus promoting fibrosis in endometriosis." (PMID 38735939, 2024). "The results revealed that knockdown of TRIM33 significantly enhanced the protein expression of TGFBR1/p-SMAD2/α-SMA/FN1, suggesting that the reduced levels of TRIM33 protein in ectopic tissues may exacerbate endometriosis-associated fibrosis." (PMID 38735939, 2024). "The TGF-β1/SMAD2 signalling pathway could be speculated to be involved in the pathological process of endometriosis." (PMID 31903498, 2020). "Because TGF-β1 could induce EMT by activating the SMAD2 signalling pathway, and given that miR-141 is down-regulated in endometriosis, we further investigated the possible influence of miR-141 on TGF-β1-induced EMT." (PMID 31903498, 2020). "miR-141 via inhibiting the TGF-β1/SMAD2 signaling pathway could inhibit TGF-β1-induced EMT in endometriosis." (PMID 32850438, 2020). "Consequently, we hypothesize that reduced TRIM33 expression in endometriotic tissues may contribute to the development of endometriosis fibrosis by enhancing TGFBR1/p-SMAD2/α-SMA/FN1 expression." (PMID 38735939, 2024). "Upregulation of Smad2/Smad3 in macrophages upon exposure to eutopic and ectopic endometrial homogenates as well as serum of women with endometriosis was observed, and blockage of Smad2/Smad3 with their inhibitor SB431542 could reverse the macrophage polarization from M1 to M2." (PMID 30276219, 2018). "miR-141 has been identified as a novel driver of EMT in endometriosis, with a possible link existing between miR-141 and the TGF-β1/SMAD2 signaling pathway in the context of endometriosis, and underscoring the role of EMT in the development of endometriosis." (PMID 34449536, 2021). "The levels of TGF-β1/SMAD2 signalling and EMT markers expression in eutopic and ectopic endometria of endometriosis were determined by immunohistochemistry and western blot analyses." (PMID 31903498, 2020). "We identified miR-141 as a novel inhibitor of the TGF-β1/SMAD2 signalling pathway and subsequently of EMT in endometriosis." (PMID 31903498, 2020). "In summary, the present study proves that miR-141 is an inhibitor of the TGF-β1/SMAD2 signalling pathway, and results in the inhibition of TGF-β1-induced EMT in endometriosis." (PMID 31903498, 2020). "Preincubation with the Smad2/Smad3 inhibitor SB431542 resulted in a decrease in the percentage of CD163+ cells, which was only observed in macrophages treated with serum from endometriosis patients." (PMID 30276219, 2018). "Western blot analysis showed that the protein expression of Smad2 and Smad3 was increased in THP-1 cell-derived macrophages treated with serum from endometriosis patients in the presence of LPS, as compared with that in control cells." (PMID 30276219, 2018). "Considering these findings together, we speculated that TGF-β1/SMAD2 signalling might mediate EMT to promote cellular proliferation and invasion in the pathogenesis of endometriosis." (PMID 31903498, 2020). "Nodal expression was significantly higher in endometriosis and OCCCa lesions as compared to that of non-OCCCas, with positive correlations to phosphorylated forms of both Smad2 (pSmad2) and GSK-3β." (PMID 30943930, 2019).
Nephropathy (7 papers, 2014 to 2022). A nonspecific term referring to disease or damage of the kidneys. "Plenty of researches have proved the role of Smad2/3 in kidney disease." (PMID 32957963, 2020). ",A number of anti-fibrotic agents, including Norcantharidin, Cordyceps sinensis, IL-7, proteasome inhibitor(MG132 and lactacystin), mycophe and PXS25 have been shown to inhibit the TGFβ1-induced Smad2 pathway in both animal models of renal disease and in cultured tubular cells." (PMID 25658916, 2015). "Similar findings have been made in studies with nephropathy models where suppression of TGF-β and p-Smad2/3 expression or a decrease in Smad2 and an increase in inhibitory Smad7 have been detected." (PMID 25071589, 2014). "Additionally, disruption of Smad2 also reduced RIPK1 and RIPK3, the central regulators in necroptosis in cisplatin nephropathy." (PMID 31754396, 2019). "The activation of the VDR promoted the reduction in the renal microvasculature disturbances by attenuating the TGF-β1/Smad2/3-dependent and downregulation of Ang-2 and AT1 expression, regulating the Angs/Tie-2 and VEGF/VEGFR2 axes, which presents disturbances in ADR-induced nephropathy in rats." (PMID 36558475, 2022).